CD4 (CD4 molecule)
Diseases named in the same sentence as CD4 in open-access papers (continued):
Sharing a sentence is not in itself a finding about the gene and the disease.
lung disease (continued). "Our findings revealed that the knockout of Havcr2 resulted in a further increase in CD4+ T cell expression in the lungs, indicating that Tim3 functions as an inhibitory factor for CD4 expression and that the absence of Havcr2 exacerbated lung disease associated with tobacco exposure." (PMID 39555065, 2024). "Using the expressions of PD‐1, chemokine C–C motif receptor 7 (CCR7), CD45RA, CD38 and HLA‐DR, we analyzed proportion of exhausted and activated CD4+ and CD8+ T cells in healthy volunteers and patients with lung diseases, respectively." (PMID 34841705, 2021). "Major populations of regulatory T cells studied in the context of lung diseases are natural thymic-derived CD4+CD25+Foxp3+ Treg cells and peripherally antigen-induced CD4+ Treg cells, which comprise both Foxp3-positive and –negative populations." (PMID 21072213, 2010). "In patients exposed to thoracic cavity radiotherapy, however, both increased and decreased bronchoalveolar lavage CD4/CD8 ratios, compared to those of untreated controls, have been reported, thus a link of these measures to lung disease outcome, if any, remains undefined." (PMID 41261392, 2025). "Furthermore, a significant positive correlation was observed between CD4+ CXCR5+ lymphocyte levels and the severity of lung disease according to the Medsger disease severity index." (PMID 38280030, 2024). "This indicates that OC43-elicited CD4+ T cells contribute to cross-protection against SARS-CoV-2 infection but do not significantly affect lung disease at day 3 after infection." (PMID 38278784, 2024). "In addition, the deactivation of CD4 and CD8 T cells in lung tissue and the reduction of their capability to generate proinflammatory cytokines was reported in vivo for lung disorder therapy using NPs." (PMID 37538179, 2023). "Finally, we reported on CD4+ and CD8+ lymphocytes and their subsets, although neutrophils and alveolar macrophages are known to play major roles in the context of pulmonary disease." (PMID 36366495, 2022). "These included the activation of co-inhibitory and co-stimulatory immune checkpoints, revealed as Hub genes, in the pulmonary disease, which may have an impact on activation of CD8+ and CD4+ T cells and other T-cell related-pathways." (PMID 34851149, 2022). "The number of CD4+ TCM and CD4+ TEM varied among lung diseases, of which quiescent CD4+ TEMs are present within the microenvironment of human LC and contribute to tumour cell apoptosis by releasing inflammatory mediators, secreting IFN‐γ and induce cell proliferation." (PMID 34841705, 2021). "CD4+ T cells play a pivotal role in the pathogenesis of CS-induced pulmonary disease, which has no proven curative therapy." (PMID 31379467, 2019). "In the SR-triggered farmer's lung disease model, Foxp3+ CD4+ T cells are the majority of the IL-10-producing LAG3+CD49b+ T cell subset in the lungs, however, there are similar percentages of Foxp3− CD4+ and CD8+ T cells (16% each)." (PMID 30510554, 2018). "Widespread evidence of pulmonary disease presented here adds to the case for treatment of all HIV-infected children with antiretrovirals irrespective of CD4 count." (PMID 26407277, 2016). "All (100%) of the 18 subjects with CD4 between 60–100 cells/μl presented with a single system involvement of CMV EOD which included 61.1% (11/18) isolated retinitis, 27.8% (5/18) isolated GIT and 11.1% (2/18) cases with isolated pulmonary disease." (PMID 25679798, 2015). "In contrast, a CD4/CD8 T lymphocyte ratio exceeding 1.5, which lacked predictive value in other lung diseases (5.9 vs. 5.7 years, p = 0.879), was associated with significantly shorter third-quartile overall survival (Q3-OS) in HP patients (8.9 years vs. not reached, p = 0.011)." (PMID 41301706, 2025).
lung disease (continued). "Additionally, single-cell RNA sequencing of lung tissue highlighted several immune cell types that may be involved in the pathophysiology of MDA5+ DM lung disease, including ISG15+ CD4+ T cells, ISG15+ CD8+ T cells, and proliferating CD8+ T cells." (PMID 39588376, 2024). "For example, numbers of CD4+CD25+Foxp3+ T cell, subsets of Tregs, are elevated upon TB infection leading to suppression of T-cell mediated IFN-γ production, and IFN-γ knockout mice infected with M. massiliense showed progressive pulmonary disease and accumulation of Tregs in the lungs." (PMID 32375214, 2020). "However, a reduced T cell lung infiltration could also have contributed to a better disease outcome, as we have previously shown that both CD4 and CD8 T cell play a role in pathogenesis of hMPV-mediated lung disease." (PMID 24205331, 2013). "CD4+ T cell subsets were measured in lung tissue obtained from patients with IPF at the time of lung transplantation, and from age- and gender-matched organ donors with no known lung disease." (PMID 27933058, 2016).
metastatic tumors (70 papers, 2011 to 2026). "Furthermore, we found that metastatic tumors with higher surface PD-L1 expression were associated with a CD4-high/Foxp3-high TIL subpopulation (p = 0.015), which would denote an unfavorable immune microenvironment in untreated patients." (PMID 26317902, 2015). "CD8+ T cells were significantly less frequent in metastatic tumors, whereas both CD4+ and CD8+ T cells present in primary tumors expressed more transcription factors associated with suppressive properties, including FoxP3 and RORγt." (PMID 41418102, 2026). "Further analysis comparing patients with metastatic disease revealed depletion of circulating CD4 and CD8 T effector memory cells, MAIT and γδ T cells in high metastatic burden cases." (PMID 40340807, 2025). "There was an increase in the population of CD4+ alpha beta T cells in the immune compartment of metastatic tumor compared to the primary tumor." (PMID 38255741, 2024). "While CD8 + T cells are traditionally recognized as key anti-cancer effectors, the use of ACT of CD4 + TILs showed a remarkable regression of tumor burden in patients with metastatic tumors." (PMID 38630265, 2024). "In that model, CD4+ T cells were found to be responsible for the anti-tumor response both at the orthotopic and the metastatic tumor site." (PMID 36980805, 2023). "A phase Ib trial in patients with high TMB metastatic tumors demonstrated that personalized neoantigen vaccine plus anti‐PD‐1 induced neoantigen‐specific CD4+ and CD8+ T cell responses, with antitumor capability." (PMID 37986697, 2023). "In the metastatic disease group, Kaplan-Meier analysis showed that higher CD3 +, CD4 +, and CD45 + were significantly associated with longer PFS, higher CD4 +, and CD45 + were significantly associated with longer OS." (PMID 35242718, 2022). "Compared with the adjacent normal tissues, the proportions of CD4+ Th and CD4+ T‐reg cells in primary and lymph node metastatic tumors were increased, whereas the level of infiltrated CD8+ T cells was lower, representing an immunosuppressive TME." (PMID 34185421, 2021). "Pre-therapy CD4+ TEM cell expansion occurs primarily during autumn or winter in patients with metastatic disease and high cytomegalovirus (CMV)-specific serum antibody titres." (PMID 33664251, 2021). "Localised non-metastatic disease: initiate full chemoradiation in patients with CD4 count higher than 240 cell/mm3; cisplatin or mitomycin offer similar outcomes." (PMID 32565901, 2020). "Weak associations were found between CD4+ and CD3+ T-cell density in matched primary and metastatic tumors, with r = 0.3 and 0.4, respectively." (PMID 26317902, 2015). "Paraffin sections from patients with (n = 9) or without (n = 9) progressive endometrial cancer (recurrent or metastatic disease) were assessed for the presence of CD4+ (helper), CD8+ (cytotoxic) and Foxp3+ (regulatory) T-lymphocytes and PR expression." (PMID 22295114, 2012). "VTN showed positive associations with CD4+ T cells and dendritic cells in metastatic tumors, but negative correlations with NK cells and eosinophils." (PMID 40943183, 2025). "A randomised study of autologous DCs co-cultured with CIKs plus IFNα vs. no adjuvant therapy in patients post-surgical resection for RCC demonstrated a reduction in recurrence and metastatic disease (p < 0.01), with increased CD4+/CD8+ ratios and reduced CD4+/CD25high populations." (PMID 38539542, 2024). "Moreover, the tumor-specific memory CD4+ T cell can prevent mice from tumor metastasis, and the tumor-specific effector CD4+ T cells can also mitigate the established metastatic tumor." (PMID 35784297, 2022). "Notably, CD4+ Treg fraction did not change in lungs of treated mice, suggesting that BEMPEG selectively increased the effector CD4+ T‐cell fraction at the primary site of metastatic tumor lesion development." (PMID 33152115, 2021).
metastatic tumors (continued). "An important question that remains unanswered is whether the presence of a memory CD4+ T cell pool limits the establishment of secondary/metastatic tumors by affecting the tumor microenvironment." (PMID 31379821, 2019). "Furthermore, according to an evaluation using immunohistochemistry, the density of TIL subsets, such as CD4+, CD8+ and FOXP3+ TILs, in the primary tumor was significantly associated with that in the metastatic tumor." (PMID 29614981, 2018). "Furthermore, the number of CD4+, CD8+ and FOXP3+ TILs in the primary tumor was also significantly associated with these numbers in the metastatic tumor (r = 0.634, p = 0.001; r = 0.700, p < 0.001; r = 0.559, p = 0.006, respectively)." (PMID 29614981, 2018). "Immune subset analyses revealed that the combination therapy not only enhanced CD4+Foxp3- T-cell expansion at the metastatic tumor site (lung) and in the periphery (spleen and DLN), but also augmented memory formation compared to the untreated and monotherapy controls." (PMID 29207606, 2017). "The sequence for Vβ2 in CD4+ cells of Bird 11 revealed one highly over-represented sequence in all sites (ILRDRGW) that may represent a metastatic tumor and a second in the spleen (IRLGTGGY)." (PMID 21573129, 2011). "Indeed, elevated signature scores of Treg and Th1 were linked to worse outcomes in both patients with primary and metastatic liver tumors, suggesting the impairment of CD4+ T cells and their promoting effects on immune escape of primary and metastatic tumor cells in the liver." (PMID 38414027, 2024). "ENTPD1 expressed on CD4+Foxp3+ regulatory T cells (Tregs), and in mice, it could inhibit natural killer (NK) cells and promote hepatic metastatic tumor growth, whereas inhibition of the enzymatic activity of ENTPD1 could be used as an adjunct therapy for hepatic malignancies." (PMID 36998605, 2023). "Furthermore, the percentages of tumor-infiltrating lymphocytes (TILs), CD8+ cells, and CD4+ T cells are lower in the metastatic tumors of TNBC compared to primary tumors, implying that immune escape may play an important role in tumor metastasis." (PMID 33042828, 2020). "Furthermore, high PD-L1-expressing metastatic tumors, but not the corresponding primary lesions, were associated with TILs that contained high densities of both CD4+ and Foxp3+ T-cells." (PMID 26317902, 2015). "Between the primary and metastatic tumors, the CD8 T-cells, activated CD4 memory T-cells, and neutrophils were significantly higher in metastatic tumors based on Wilcoxon statistical p-values < 0.05." (PMID 37400526, 2023). "Compared with other groups, the CP+-CpG NPs group resulted in a significant increase in the proportion of CD4+ T cells and CD8+ T cells, which indicated successful activation of the immune effects and inhibition of primary and metastatic tumors." (PMID 38004595, 2023). "This also corresponded to an increased CD4:CD8 T cell ratio, and enrichment of regulatory T cells in the local nodal microenvironment in metastatic disease." (PMID 34439160, 2021). "In our experiments, we observed that the ratio of CD4+/CD8+ T cells and the expression of PD-L1 in primary and metastatic tumors were all suppressed by the TNuF supplement, which are correlated with the influence of TNuF on the abscopal effect of RT." (PMID 32872195, 2020). "In contrast, in the presence of CD4 help all the DDR pathways are up regulated, resembling those present in metastatic tumors." (PMID 26485718, 2015). "This discordance can likely be attributed to the CD4+ helper T-cell content, as the remaining two subsets examined, CD8+ cytotoxic T-cells and Foxp3+ TILs, were concordant between primary and metastatic disease." (PMID 26317902, 2015). "Increased frequencies of CD4 and CD8 cells were seen in both intra-tumoral and peritumoral regions of metastatic tumor specimens obtained between 3 and 15 days after treatment initiation." (PMID 24194739, 2013).
metastatic tumors (continued). "Several studies have shown that fusion cells have the potential to induce CD4+ as well as CD8+ T-cell mediated antitumor immunity, protection from an otherwise lethal challenge of tumor, and even regression of established metastatic disease." (PMID 21943054, 2011). "Regarding immune cell composition, primary and metastatic tumors were mainly characterized by CD8+ Texh, CD4+ Treg, neutrophils, and CD4+ conventional T cells (Tconv), whereas the para-tumor region was dominated by granulocyte lineages, including neutrophils, monocytes, and macrophages." (PMID 39231924, 2024). "Interestingly, the combination of anti-CSF1R and anti-PD-1 treatment further significantly inhibited metastatic tumor progression in the liver and enhanced IFN-γ+ CD8+/CD4+ and Ki67+ CD8+/CD4+ T-cell infiltration in the tumor microenvironment." (PMID 37872170, 2023). "Additionally, via immunohistochemistry the vaccinated mice showed a significant increase in the infiltration of CD4 and CD8 T cells in the metastatic tumors." (PMID 37434263, 2023). "In another study, a lower CD4+ T-cell count in venous blood was reported in patients with metastatic disease compared to those without metastasis." (PMID 36005179, 2022). "Thus, we need to systematically dissect the function of the different CD4+ and CD8+ TRM cell subsets from different tissues and from various primary and metastatic tumors." (PMID 36385379, 2022). "Although not significant, one study suggested that there was a tendency toward decreased levels of CD3+CD4+ T helper cell and increased levels of CD3+CD8+ T-cells in the peripheral blood of patients with advanced metastatic tumors responding to anti-PD-1 antibody." (PMID 32183719, 2020). "Interestingly, this study reported that the CD8/CD4 ratio and CD8/CD68 ratio were significantly reduced in metastatic tumors compared with the corresponding primary tumors, suggesting a tolerogenic and tumor-promoting microenvironment at the metastatic site." (PMID 33352665, 2020). "Increased macrophage infiltration in MYC/Twist1 primary and metastatic tumors with no change in neutrophils or CD4 T cells infiltration was confirmed by IHC." (PMID 31933479, 2020). "In addition, according to the immunohistochemistry evaluation, the density of CD4+, CD8+ and FOXP3+ TILs in the primary tumor and that in the metastatic tumor were significantly correlated with that in the metastatic tumor." (PMID 29614981, 2018). "Cells from these tumor masses and metastatic tumors had CD4/CD8 flow cytometric profiles indistinguishable from the original transplanted donor cells." (PMID 23457589, 2013). "After H@Gd-NCPs sensitized radiation, CD4+, and CD8+ T cell infiltration significantly increased in both irradiated and non-irradiated tumors, potentiated immune checkpoint inhibitors, and extended radiation therapeutic effects to distant and metastatic tumors for long-term survival." (PMID 33420008, 2021). "Our analysis depicted for the first time that: a) a significant percentage of CD8+ and CD4+ lymphocytes exhibits a senescent phenotype in the TC, whereas in the NAT the percentage of these cells is significantly lower and b) the senescence phenotype correlates with metastatic tumor in lymph nodes." (PMID 32645996, 2020). "Notably, significant differences in the scores for CD4 T cells, CD4 T central memory cells, CD4 T effector memory cells, CD8 T cells, naïve B cells, memory B cells, class-switched memory B cells, and epithelial cells were observed between primary and paired metastatic tumors." (PMID 35626050, 2022). "Analysis of other T cell subpopulations (CD4+, CD8+ and γδ T cells), interstitial macrophages, eosinophils, B cells and NK cells revealed no significant change in primary versus metastatic tumors." (PMID 35145525, 2022).
metastatic tumors (continued). "Analysis indicated that the primary tumors and metastatic tumors had a significantly lower ratio of CD8+ to Tregs than in normal bowel tissue, whereas there was a significantly lower ratio of CD4+ to Tregs than in blood." (PMID 35320356, 2022). "Increased infiltration of metastatic tumors with both CD4 and CD8 cells in one study, and of CD8 cells, but not CD4 cells in another study was observed after treatment with BRAF inhibition." (PMID 24194739, 2013). "Although brain tumors did develop in mice with tumor-specific immunologic memory receiving α-CD4 and α-CD8 depleting antibodies, survival was significantly longer than naïve mice (p<0.01), suggesting additional non-T cell dependent mechanisms of immune memory against metastatic tumors in the brain." (PMID 32690669, 2020). "In contrast to CD8 responses in the absence of CD4 help, when CD4 help is present, DNA damage sensing is adequate and all DDR pathways are up regulated ensuring adequate cell survival during division, resembling the DDRs gene expression reported in metastatic tumors." (PMID 26485718, 2015).